REN (renin)
Diseases named in the same sentence as REN in open-access papers (continued):
Sharing a sentence is not in itself a finding about the gene and the disease.
metabolic syndrome (159 papers, 2007 to 2026). A cluster of metabolic risk factors for CARDIOVASCULAR DISEASES and TYPE 2 DIABETES MELLITUS. "Various inflammatory parameters, traits of the metabolic syndrome, lipidome and metabolome parameters, fat distribution, and carotid atherosclerosis were associated with plasma aldosterone and renin levels." (PMID 32529242, 2020). "In line with this, aldosterone and renin associated with metabolic syndrome scores based on the National Cholesterol Education Program (NCEP) criteria." (PMID 32529242, 2020). "Aldosterone and renin are both strongly associated with the presence of metabolic syndrome, and patients with metabolic syndrome displayed higher aldosterone and renin concentrations." (PMID 32529242, 2020). "NAFDL is associated with atherogenic dyslipidemia, inflammation and renin-angiotensin system (RAS) imbalance, which in turn lead to atherosclerotic lesions." (PMID 28505074, 2017). "UA has the effect of promoting oxidation and inflammation, which could cause microvascular injury by stimulating the renin‐angiotensin system, inhibiting the proliferation of endothelial nitric oxide, and participate in metabolic syndrome." (PMID 37961994, 2024). "Surprisingly, aldosterone and renin were associated with metabolic syndrome via different traits." (PMID 32529242, 2020). "Interestingly, the association with metabolic syndrome was established through different traits for aldosterone and renin." (PMID 32529242, 2020). "Moreover, recent studies have implicated the renin-angiotensin system, which is upregulated in metabolic syndrome, in aortic valve disease pathogenesis." (PMID 24767168, 2014). "Studies have shown that the renin–angiotensin system is associated with the VLF band and plays a stronger role in cardiovascular disease prognosis, metabolic syndromes, and all-cause mortality after traumatic brain injury than other HRV components." (PMID 40563818, 2025). "The activation of the renin-angiotensin system (RAS) has been related to various aspects of metabolic syndrome." (PMID 37173649, 2023). "Dyslipidemia, IR, an inflammatory environment, and the renin-angiotensin system activation are currently considered pathophysiological mechanisms linking AF and NAFLD." (PMID 37158953, 2023). "Açaí treatment increased insulin receptor expression, prevented dyslipidemia, and decreased renin and angiotensin II type 1 receptor (AT1 receptor) expression, the latter of which was linked to reduced renin and angiotensin II plasma levels." (PMID 36839349, 2023). "The average research period for SSH in this field is around 2020, closely tied to keywords such as inflammation, renin-angiotensin system, SCFAs, and metabolic syndrome." (PMID 37899834, 2023). "These include redox stress, inflammation, islet fibrosis, an active role of metabolic syndrome, systemic and tissue islet renin–angiotensin–aldosterone system, amyloid deposition, and β-cell dysfunction and apoptosis." (PMID 36769807, 2023). "The RAAS (renin–angiotensin–aldosterone system) pathway also triggers the neurohumoral activation, which in turn contributes to the development of metabolic syndrome." (PMID 35268685, 2022). "The reduced expression of Agtr2 in IUGR-R animals relative to macrosomic animals is also interesting since it is thought that an overactive renin-angiotensin system (RAS) is involved in metabolic syndrome." (PMID 35208177, 2022). "Activation of the renin-angiotensin system with dyslipidemia synergistically accelerates tubulointerstitial injury in mice." (PMID 35630319, 2022). "Such efforts strategies include intensive control of glycemia, strict blood pressure control, dyslipidemia correction, discontinuation of smoking and nephrotoxic drugs, and renin-angiotensin system blockade to minimize the pressure of glomerular capillary." (PMID 34931960, 2021).
metabolic syndrome (continued). "ACE and ACE2, that orchestrate together with CD10 the Renin-angiotensin system, play an important role in metabolic syndrome and liver disease development 48,49." (PMID 34131392, 2021). "IL-6 also promotes the expression of adhesion molecules by endothelial cells and activates the local renin-angiotensin system, whose activation contributes to metabolic syndrome development." (PMID 32466598, 2020). "Aliskiren (a renin inhibitor) has been reported to improve hyperglycemia, dyslipidemia, and vascular function in rodent and human studies." (PMID 32235782, 2020). "The sympathetic nervous system, renin-angiotensin system, inflammatory cytokines, and hyperdynamic circulation play an important pathophysiologic role in metabolic syndrome." (PMID 31965377, 2020). "According to past studies, metabolic syndrome increases eGFR through the regulation of system activities of renin-angiotensin-aldosterone and sympathetic nerve, resulting in increased glomerular hyperfiltration." (PMID 31369578, 2019). "Renin–angiotensin system in visceral fat plays a crucial role in the pathogenesis of metabolic syndrome in fructose-fed rats." (PMID 28700686, 2017). "Further, the effects of renin inhibition on visceral adiposity in metabolic syndrome are currently under investigation." (PMID 28700686, 2017). "These are blood pressure controling, inhibition of the renin-angiotensinaldosterone axis, improving glycemic control, improving dyslipidemia, improving protein uriaand lifestyle modifications." (PMID 25093156, 2014). "Many new, profound and interacting mechanisms link hypovitaminosis D with other correlates of the metabolic syndrome, including renin regulation." (PMID 18226257, 2008). "Components of the metabolic syndrome may stimulate dysregulation of the Renin-Angiotensin-Aldosterone System, modulated by ACE-2, leading to increased presence of Angiotensin II." (PMID 40989546, 2025). "Previous studies have shown that the renin–an giotensin system is associated with the VLF band, with a stronger correlation to cardiovascular disease prognosis, metabolic syndromes, and all-cause mortality following traumatic brain injury compared to other HRV components." (PMID 40563818, 2025). "In addition, the aldosterone-induced activation of the MR in response to renin secretion promotes the disruption of the glomerular filtration barrier and development of proteinuria in animal models of metabolic syndrome." (PMID 36143852, 2022). "During this period, metabolic syndrome and chronic activation of the renin-angiotensin-aldosterone system may play a key role in the exacerbation of LV contractility." (PMID 34521391, 2021). "Of the traits that constitute metabolic syndrome, aldosterone, but not renin, was associated with triglyceride concentrations." (PMID 32529242, 2020). "Furthermore, the renin-angiotensin system (RAS) becomes inappropriately activated during metabolic syndrome, increasing oxidant production." (PMID 29049981, 2018). "Thus, in the present study, we aimed to evaluate the effect of aliskiren, a direct renin inhibitor, on metabolic syndrome-related NASH." (PMID 29046730, 2017). "This is explained by an upregulation of the renin-angiotensin system and a reduction of glutathione and glutathione peroxidase in erythrocytes, resulting in higher concentrations of reactive oxygen species which again promote the metabolic syndrome." (PMID 22657586, 2012). "We will review possible mechanisms of progressive renal damage, including systemic and glomerular hypertension, various cytokines and growth factors, with special emphasis on the renin–angiotensin–aldosterone system (RAAS), podocyte loss, dyslipidemia and proteinuria." (PMID 17647026, 2007).
metabolic syndrome (continued). "Calcium reduces blood pressure by modulation of smooth muscle reactivity and vitamin D may reduce dyslipidemia and improve blood pressure through maintenance of calcium homeostasis, stimulation of insulin production and release, and regulation of the renin–angiotensin–aldosterone system." (PMID 28228848, 2017). "In preHTN, the increase in body weight affects the renin-angiotensin-aldosterone system (RAAS) regulation mechanism, while in metabolic syndrome, excess weight increases glucose levels and IR, leading to the activation of the RAAS system." (PMID 40071249, 2024). "This is in line with studies that have shown the capability of renin–angiotensin system inhibitors to modulate glomerular HPSE expression and restore HS in experimental models of metabolic syndrome and in adriamycin nephropathy." (PMID 38003732, 2023). "Though specific populations seem to benefit more from direct renin inhibition by ALI (e.g., obese, metabolic syndrome and resistant hypertension) for others, it is just another viable option in the armory of clinicians to achieve adequate BP control." (PMID 28598381, 2017). "The prevalence of dyslipidemia was higher in low PLR group (41.7% vs. 20.0%, P = 0.048), whereas the percentage of renin-angiotensin system (RAS) blocker usage was lower in low PLR group (19.4% vs. 45.7%, P = 0.018)." (PMID 28673240, 2017). "Studies in a rat model of metabolic syndrome, bilateral RDN significantly reduced plasma renin activity, and prevented progression of kidney injury and cardiac remodeling." (PMID 27277003, 2016). "Using univariate regression analysis, UACR was correlated with age, male gender, waist circumference, BMI, SBP, serum creatinine, uric acid, fasting plasma glucose, dyslipidemia, salt intake, ECG voltage, and use of inhibitors of the renin-angiotensin system." (PMID 23830507, 2013). "More patients with metabolic syndrome received a renin–angiotensin–aldosterone system (RAAS) inhibitor or a statin than those without metabolic syndrome (for RAAS inhibitors: 63.2% vs. 14.3%, p = 0.017; for statin: 63.2% vs. 0%, p = 0.002)." (PMID 37233658, 2023). "Thus, it is possible that the renin-angiotensin system is not involved in the cognitive decline occurring after PE, but rather highlights a role for maternal dyslipidemia." (PMID 35615682, 2022). "However, the effects of renin inhibition on visceral adiposity in metabolic syndrome are not fully investigated." (PMID 28700686, 2017). "However, since renin is the first and rate-limiting step of the RAS and LXR-alpha plays a vital role in the pathophysiology of dyslipidemia, the link between RAS and LXR-alpha in MSCs further complicates the role of RAS in the relationship between MSC adipogenesis and metabolic syndrome." (PMID 27313625, 2016). "Additionally, an experimental study showed that dyslipidemia may activate angiotensin II endothelial injury and lipid peroxidation by an AT1 receptor-mediated mechanism, suggesting an interaction between the renin-angiotensin-aldosterone system and lipid metabolism." (PMID 21827713, 2011).
primary aldosteronism (141 papers, 2009 to 2026). An endocrine disorder characterized by excessive production of aldosterone by the adrenal glands. "Primary aldosteronism (PA), a major cause of secondary hypertension, is endocrinologically characterised by autonomous aldosterone oversecretion and renin suppression." (PMID 41066530, 2025). "Recent evidence suggests that reversal of renin suppression is associated with better cardiovascular health in people with primary aldosteronism." (PMID 39026100, 2024). "Background and aim: Aldosterone-renin ratio (ARR) is an important screening tool for the assessment of primary aldosteronism as a cause of secondary hypertension." (PMID 37065379, 2023). "For diagnosis of the disease, aldosterone level and renin activity are measured, and aldosterone / renin activity ratio is very often utilized as established diagnostic criteria for primary aldosteronism in clinical practice." (PMID 36271288, 2022). "Plasma aldosterone concentration and plasma renin activity are the major diagnostic biomarkers in primary aldosteronism." (PMID 35204632, 2022). "Primary aldosteronism (PA) is a heterogeneous group of disorders caused by autonomous overproduction of aldosterone with simultaneous suppression of plasma renin activity (PRA)." (PMID 34829937, 2021). "Primary aldosteronism (PA) is a heterogeneous group of disorders caused by the autonomous overproduction of aldosterone with simultaneous suppression of plasma renin activity (PRA)." (PMID 34829937, 2021). "Hyperaldosteronism can occur either as primary aldosteronism (renin-independent) or secondary aldosteronism (renin-dependent).As the most common cause of secondary hypertension, primary aldosteronism is associated with increased cardiovascular risk." (PMID 34867798, 2021). "Primary aldosteronism (PA) is a potentially curable form of secondary hypertension caused by excessive renin-independent aldosterone secretion, leading to increased target organ damage and cardiovascular morbidity and mortality." (PMID 34054559, 2021). "Primary aldosteronism (PA) is a potentially curable form of secondary hypertension caused by excessive renin-independent aldosterone secretion." (PMID 34054559, 2021). "Primary aldosteronism (PA) is characterized by excessive and autonomous aldosterone production and suppressed plasma renin and is commonly caused by aldosterone-producing adenoma (30%-50%) and bilateral adrenal hyperplasia (50%-65%)." (PMID 31354984, 2019). "Increased renin level can be faced in secondary hyperaldosteronism, whereas decreased renin is usually found in Conn’s syndrome, associated with high aldosterone level." (PMID 25368694, 2015). "Primary aldosteronism is characterized by inappropriately high, autonomous aldosterone secretion, associated with low serum renin concentrations." (PMID 22848660, 2012). "Primary aldosteronism (PA), which accounts for 5% to 10% of patients with hypertension, is characterized by autonomous adrenal secretion of aldosterone with suppressed renin activity, and represents a leading cause of secondary hypertension." (PMID 41204571, 2025). "Thus, in the pathological state of autonomous, renin-independent aldosterone production, a condition known as primary aldosteronism (PA), affected individuals face an increased risk of renal, metabolic, and cardiovascular diseases." (PMID 40863169, 2025). "In my view it is better to measure both renin and aldosterone so that renal tubular sodium channel variants and other factors affecting the function of the renal sodium channel (adducin, endogenous ouabain) can be differentiated from primary aldosteronism." (PMID 21532778, 2010). "The patient had been on lisinopril for resistant hypertension, which can raise renin levels and lower the aldosterone-to-renin ratio, masking existing primary aldosteronism." (PMID 41356982, 2025). "Hypersecretion of aldosterone and inhibition of renin are the pathophysiology of primary aldosteronism, leading to abnormal elevation of ARR." (PMID 40395817, 2025).
primary aldosteronism (continued). "Primary aldosteronism should be considered in hypertensive or hypokalemic patients by calculating the aldosterone / renin ratio." (PMID 41209753, 2025). "Primary aldosteronism (PA) diagnosis is a multistep process that begins with screening based on the plasma aldosterone-to-renin ratio (ARR)." (PMID 39999127, 2025). "Primary aldosteronism testing revealed that plasma aldosterone and renin activity were both elevated at 30 ng/dL and 37 ng/mL/h, respectively." (PMID 40704299, 2025). "Laboratory investigations confirmed the classic biochemical profile of licorice toxicity, characterized by suppressed aldosterone and renin levels, effectively differentiating it from other conditions such as Conn's syndrome." (PMID 39498427, 2024). "After case detection, according to the Endocrine Society Guidelines 2016, patients who had a positive aldosterone renin ratio (ARR) result should undergo one or more confirmatory tests to confirm or exclude primary aldosteronism." (PMID 38978003, 2024). "In contrast, conditions such as Conn's syndrome (primary hyperaldosteronism) typically present with elevated aldosterone levels and low renin due to an aldosterone-secreting adrenal adenoma." (PMID 39498427, 2024). "Primary aldosteronism is suspected when decreased plasma renin activity (PRA) and increased aldosterone levels occur." (PMID 39184766, 2024). "Excessive aldosterone secretion is referred to as aldosteronism and is classified as primary (Conn’s syndrome with low renin/angiotensin II) or secondary (high renin/angiotensin II)." (PMID 39518893, 2024). "As a result, primary aldosteronism provides a unique clinical model for studying the effects of excess aldosterone on the heart because these effects are distinct from those of the renin-angiotensin axis." (PMID 38425104, 2024). "The aim of this study is to evaluate performance of aldosterone-to-renin ratio (ARR) before washout of antihypertensive drugs as a screening test for primary aldosteronism (PA)." (PMID 38381080, 2024). "Recent guidelines define primary aldosteronism (PA) as a group of disorders in which aldosterone production is inappropriately high and relatively autonomous from the physiological control of the renin–angiotensin system." (PMID 39452270, 2024). "The biochemical profile of primary aldosteronism typically shows an elevated plasma aldosterone, suppressed renin, and occasionally low potassium levels." (PMID 38978003, 2024). "Primary aldosteronism, marked by high aldosterone and suppressed renin levels, is often under-recognized, despite its prevalence of up to 20% in resistant hypertension." (PMID 39452270, 2024). "Primary aldosteronism is characterized by autonomous aldosterone production in the presence of renin suppression." (PMID 39026100, 2024). "Correctly diagnosing primary aldosteronism entails an initial case-detection testing which involves obtaining a morning blood sample of plasma aldosterone concentration, plasma renin activity or plasma renin concentration in a seated position." (PMID 38978003, 2024). "Second, outside of pregnancy, the elevated aldosterone-to-renin ratio in patients with primary aldosteronism results from renin-independent secretion of aldosterone leading to suppression of renin (as part of a regulatory negative feedback loop)." (PMID 38001956, 2023). "Another limitation is that only one measurement of aldosterone and renin was performed and the number of participants with likely primary aldosteronism was small (N = 16)." (PMID 37690031, 2023). "The clinical utility of the aldosterone-to-renin ratio for detection of primary aldosteronism in pregnancy is unclear." (PMID 38001956, 2023). "Since the introduction of the aldosterone-to-renin ratio (ARR) as a screening tool for primary aldosteronism (PA), there has been a marked increase in the reported prevalence of this condition among hypertensive, even normotensive, subjects." (PMID 37335717, 2023).